IL1B (interleukin 1 beta)
Diseases named in the same sentence as IL1B in open-access papers (continued):
Sharing a sentence is not in itself a finding about the gene and the disease.
infection (continued). "Another relevant study in Microtus fortis (a non-permissive host) revealed that the levels of several cytokines including IL-1β, IL-3, IL-4, IL-10, and IL-17 increased from the second to the third week post-infection." (PMID 36339337, 2022). "In agreement with our previous results, in both reconstitution and PAMs infection assays, Sk02 WT infection induced a significantly high level of IL-1β production, however, Hf09 WT infection produced only a similar level of IL-1β as in the mock-infected cells." (PMID 35062292, 2022). "Consistent with this, when macrophages are infected with an ESX-1-mutant strain of M. tuberculosis, formation of ASC specks and secretion of IL-1β is significantly reduced compared to infection with wild-type bacteria." (PMID 35801644, 2022). "In this case, the median concentration of IL-1β is 52 pg/mL, but it can reach values up to 940 pg/mL during infection." (PMID 36358557, 2022). "During the acute phase response to injury or infection, TNFα and IL-1β are produced and they, in turn, induce the production of IL-6." (PMID 35821823, 2022). "The expression levels of inflammation-related genes, including IL-6, IL-12, IFN-β, and IL-1β, were also significantly increased after infection for 36 or 48 h." (PMID 35682869, 2022). "Moreover, IL-1β can also be produced by other inflammasomes or in an inflammasome-independent manner, so blockage of IL-1β may lead to a higher risk of infection." (PMID 35250572, 2022). "In a multivariate model testing both status and day, membership in the E16.5 group was a significant predictor for Ifnγ, Tnf, Il1β, Il10, and Cox2 abundance (p ≤ 0.0306), while holding infection status constant." (PMID 35312688, 2022). "NLRP3 inflammasome mediates the conversion of IL-1β and IL-18 to their active form in response to pathogen infection." (PMID 36339337, 2022). "Cells treated with DMSO as a vehicle control for 48 h after infection generated 224.75 ± 10.01 pg/mL of IL-1β in the culture supernatants." (PMID 36559293, 2022). "C. sinensis infection caused diminished Th1 cytokines (IL-1β, IL-2, IL-12p70, IFN-γ and TNF-α), Th2 cytokine (IL-4), as well as Th17 cytokine (IL-17A) in sera, which showed decreasing trend by infection intensity." (PMID 36083861, 2022). "The results showed that at the initial stage of infection, the expression levels of intestinal inflammatory factors such as IL-1β, IL-6, IL-10, TGF-β and TNF-α in the treatment group were much lower than those in the challenge group (p < 0.01)." (PMID 36431853, 2022). "In one, cytotoxic activities involving CD8+ T and NK cells linked to inflammatory executors such as NLRP3 inflammasome, IL-1β, and neutrophils mediate exacerbated tissue damage in response to L(V)b infection." (PMID 35770175, 2022). "ASFV HLJ/18 isolate infection induced low levels of IL-1β in PAMs, even in the presence of strong inducers such as LPS and poly(dA:dT)." (PMID 35350623, 2022). "Infection of BMDCs with M. smegmatis can induce pyroptosis; yet, co-infection experiments revealed that wild-type M. tuberculosis can block the secretion of IL-1β." (PMID 35801644, 2022). "High levels of TNF-α, IL-6, IFN-γ, and IL-1β cytokines were induced in the lung samples from naïve mice at 6 days after infection." (PMID 36146461, 2022). "Immunofluorescence microscopy revealed that IL-1β treatment mirrored the infection in PMN-HIOs with a proportion of shed epithelial cells expressing cleaved Caspase-3." (PMID 36191054, 2022). "Cytokines in the brain (TNF-α, CCL-2, CXCL-2, CXCL-10, IL-1β, IL-6, IL-17, and M-CSF) were upregulated after infection at 3 dpi, and the cytokine content gradually decreased with extension of the infection time." (PMID 36352407, 2022). "—Mixed LAB strains from wild pigs exerted a beneficial effect on the host via immunomodulation of IL-6 and IL-1b against the infection of E. coli." (PMID 36387374, 2022).
infection (continued). "Previous studies have shown that the secretion of IL-1β, which is regulated by inflammasome activation, is a critical step in the host innate immune responses to infections with various pathogens." (PMID 36326277, 2022). "We observed that SP600125 promoted the expression levels of IL-6, CCL21, IFN-β, MX, and OASL, but the expression level of IL-1β decreased in DEF cells in the presence of CHa strain infection." (PMID 35837399, 2022). "Intriguingly, ASFV-ΔH240R infection induced NLRP3 inflammasome activation to promote IL-1β secretion from PAMs." (PMID 36326277, 2022). "Concordantly, pre-treatment of THP-1 with IL-1β or IFN-β reduced infection of all viruses but with pandemic HIV-1(M) being notably less sensitive, even when target cells were pre-treated." (PMID 36289397, 2022). "Elevated activity of IL-1β and IL-6 cytokines has been observed at the nasopharynx region, which is the key site of infection where higher bioactivity of IL-6 is strongly correlated with a higher load of SARS-CoV-2." (PMID 36298704, 2022). "In fact, plasma cortisol levels, as well as the expression of the pro-inflammatory cytokine il1β, were found to be augmented by inflammation right after infection (i.e., 4 and 24 h)." (PMID 36293344, 2022). "Increased secretion of IL-1β enhances proinflammation in the site of infection, in which infection is contained and lymphocytes are activated through interaction with viral antigen-presentation cells for adaptive immunity." (PMID 35173184, 2022). "The possible pathogenetic factors include modification of cytokine balance, activation of alternate pathways such as IL-1β, and potential occult infection, a well-known trigger for HS." (PMID 35409118, 2022). "Taken together, these results show that ASFV-ΔH240R infection specifically activates the NLRP3 inflammasome to promote the secretion of IL-1β." (PMID 36326277, 2022). "Mature IL-1β is an important pro-inflammatory cytokine, responsible for tightly regulating levels of inflammation in response to infection." (PMID 36318583, 2022). "NLRP12 induces the production of inflammasome-dependent cytokines IL-1β/18 following Yersinia or Plasmodium salina infection, thereby preventing severe infections by these pathogens." (PMID 36189207, 2022). "Higher NK cell abundance correlated with increased pulmonary IFNγ levels in BALB/c mice, whereas Il1b was slightly higher in C57BL/6 animals 3 days after infection." (PMID 35023830, 2022). "Taken together, our results demonstrate that ASFV-ΔH240R infection specifically activates the NF-κB signaling to facilitate pro-IL-1β transcription." (PMID 36326277, 2022). "Our earlier findings showed that JWH133-treated mice had significantly lower BALF levels of IL-1β, whilst the level of IL-1β was significantly higher in the BALF of CB2KO mice post-PA infection." (PMID 36463179, 2022). "IL-1β protects against infection by rapid recruitment of neutrophils, induction of fever, cytokines and chemokines, and adaptive immunity." (PMID 36440291, 2022). "The expression of pro-IL-1β induced by STEC O113 ΔsubAB infection was almost completely inhibited by co-treatment with SubABwt and the ER stress inducers Tm or thapsigargin (TG)." (PMID 35345462, 2022). "Infection with PA103 or PAK wild-type strains resulted in significantly more IL-1β in wounds as compared with PBS-treated uninfected wounds (& e)." (PMID 35277504, 2022). "During early in vivo infection in mice, AMs upregulate a Nrf-dependent transcriptional program that limits IL-1β and TNF production to impair the control of Mtb33." (PMID 35173157, 2022). "Intriguingly, we observed that Listeria expressing the SPI-2 needle protein SsaG induced significantly increased IL-18 and robust IL-1α and IL-1β secretion compared to mock infection or WT Lm infection alone." (PMID 35073381, 2022). "At the end of the kinetic, almost all infections produced the same levels of IL-1β, except for the infection with BSD." (PMID 35873160, 2022).
infection (continued). "IL-1β tends to increase rapidly secreted from macrophages to activate the immune system when meeting tissue injury or infection." (PMID 35075430, 2022). "As for the protein levels of cytokine profiles in the ileum, DON infection induced dramatic increases in the expression of ileal IL-1β, TNF-α and IL-6 proteins (p < 0.01)." (PMID 36139849, 2022). "Despite its many similarities to S. Typhimurium, infection of THP-1 cells with S. Typhi triggers increased caspase-1 cleavage, IL-1β secretion and cell death – in contrast to infection with S. Typhimurium." (PMID 35801644, 2022). "Glycolysis stabilizes the transcription factor HIF-1α and increases IL-1β expression, linking metabolic and immune responses during infection." (PMID 35531332, 2022). "IL-1β secretion induced by ASFV-ΔH240R infection was approximately 4-fold higher than that of ASFV-WT at each time point, and IL-1β mRNA expression was approximately 300-fold higher at 24 hpi in PAMs." (PMID 34787458, 2022). "Although replication kinetics and virus spread and of the two deletion mutants on CCB cells was undistinguishable from wild-type KHV-T (results not shown), differential expression was documented for nfκb, il6, il10 and il1b 48 h after infection." (PMID 36068296, 2022). "The direct sensing of Eh via Gal-lectin induces NLRP3 inflammasome activation, driving the processing and release of IL-1β and an aggressive inflammatory response that are aimed at eradicating Eh and recruiting immune cells to the site of infection." (PMID 35795683, 2022). "This confirmed a significant increase in Il1b at 24 h following infection, with minimal induction of Il23a evident, as well as higher levels of monocyte and T cell chemoattractants Ccl4 and Ccl5." (PMID 35845169, 2022). "Inflammasome signaling and release of IL-1β protects against a variety of pathogens, especially in the acute phase of infection." (PMID 36177039, 2022). "In the HK, however, the transcription levels of il1b, il6, and il8 were up-regulated upon infection." (PMID 35055122, 2022). "Remarkably, deletion of both tie1 and tie2 in a Δvprh/Δhns1 background (Δvprh/Δhns1/Δtie1/Δtie2) completely abolished the cell death and IL-1β secretion observed upon infection of BMDMs with the Δvprh/Δhns1 strain, without affecting TNFα secretion." (PMID 36155655, 2022). "A well-known example is interleukin-1β (IL-1β), a potent proinflammatory cytokine critical for host response to infection, while excessive secretion of IL-1β leads to a myriad of human diseases." (PMID 35671825, 2022). "Following infection with Citrobacter 7 days earlier, the expression of transcripts for proinflammatory cytokines Il1β, Il12, and Il18 and for immunoregulatory Il10 was increased." (PMID 35140345, 2022). "We infected BMDMs of C57BL/6, Gsdmd−/−, Casp8/RIPK3−/−, and Casp8+/+/RIPK3−/− mouse strains with B. abortus, and after 17 h of infection, we evaluated the secretion of IL-1β in the supernatant of the cells." (PMID 36532444, 2022). "During an infection, IL-1β is one of the first cytokines released by macrophages, monocytes, and dendritic cells." (PMID 35464419, 2022). "The inflammation of mediators, such as NO, TNF-α, IL-1β, and IL-6, among others, is activated due to the presence of tissue damage or infection; therefore, the concentrations of these mediators increase in the damaged areas." (PMID 35890070, 2022). "The concentrations of IL-1a, IL-1b and GM-CSF in Rag2−/− mice remained at the same high level up to 20 days of infection, whereas the expression of IL-6 reached a peak on the 4th day, and then decreased to the initial level." (PMID 36016362, 2022). "Our results showed that both TNF-α, and IL-1β were down-regulated by EbSe-Ag+, contributing to host defense during infection." (PMID 35958130, 2022).
infection (continued). "Proinflammatory cytokines associated with Th17/Th1 response such as IL-6, TNF-α, and IL-1β, and neutrophil-recruiting chemokines including CCL2, CCL3, CXCL1, and CXCL2 were highly produced from day 3 to day 14 after WT infection." (PMID 35696422, 2022). "LPS stimulated IL-12, IL-17A, IL-1β, IL-6 and IL-8 were significantly higher post-infection than during antibiotic therapy, as well as Poly:IC stimulated IFN-γ, IL-1β and IL-6." (PMID 35360000, 2022). "To gain more insight into the mechanism underlying the TLR2-mediated production of TNF-α and IL-1β in monocytes, we pharmacologically targeted key molecules of signaling downstream of TLR2 prior to infection." (PMID 36240261, 2022). "and showed that IL-1β and IL-1α release was significantly impaired compared to that in infections using viable Rickettsia spp., a phenotype more strongly observed in infections using R. montanensis." (PMID 35130729, 2022). "A study conducted on diabetes-induced mice showed an elevated level of a proinflammatory cytokine (IL-1β) that was exhibited by the proinflammatory responses of altered M1 and M2 macrophages at the site of infection." (PMID 36365254, 2022). "Meanwhile, the mRNA levels of IL-6, IP-10, TNF-α, and IL-1-β were increased during reinfection but were lower than those during primary infection." (PMID 35893674, 2022). "Thus, effective neutralization of IL-1β could potentially lead to an increased risk of infection." (PMID 35632584, 2022). "Infection led to robust induction of chemokine and interleukin genes, including Il1b, Il6, Ccl2, Ccl3, Ccl4, Ccl7, Cxcl1, Cxcl2, Cxcl5, Cxcl9, and Cxcl10, and related receptor genes, including Ccr1, Ccr4, Ccr5, Ccr5, Ccr7, Cxcr2, Cxcr5, Il1r2, and Il1rn." (PMID 35487885, 2022). "The persistence of IL-17A together with other inflammatory cytokines such as IL-12p70, stem cell factor, and IL-1β was discovered in patients up to 180 days post-infection." (PMID 36186648, 2022). "The accumulation of IL-1β and neutrophils increases permeability of blood vessels which allows the infiltration of interstitial fluids to the site of infection and leads to cell apoptosis and tissue necrosis." (PMID 35077922, 2022). "Cells treated with the cell-permeant Ca2+ chelator BAPTA-AM in a dose-dependent manner exhibited a significant decrease in IL-1β secretion during SVA infection or 3D expression." (PMID 35254168, 2022). "IL-1β, originally identified as the major febrile endogenous pyrogen, has been shown to impart various responses in infection, injury, and immune challenges." (PMID 35457058, 2022). "The severity of the infection was also assessed by analyzing the levels of inflammatory cytokines, including IL-1β and IL-6, in the BAL fluid of the lungs of A. baumannii-infected mice." (PMID 36431892, 2022). "Although excessive IL-1β is immunopathological, availability of the cytokine during the early phase of infection is critical for host protection." (PMID 35173157, 2022). "The infection group showed a significant upregulation in IL-1β, IL-6, and CXCL2; the latter is homologous to IL-8 in mice (p < 0.05)." (PMID 35672331, 2022). "Infection of P. gingivalis increased the expression of IL-1β (precursor), IL-1β (mature), and TNF-α proteins in MBECs." (PMID 35453424, 2022). "The infection sustained by S. mutans is characterized by a high-level synthesis of Interleukin (IL)-1β, a proinflammatory cytokine, that is engaged by the host’s defenses against pathogens." (PMID 35893249, 2022). "A few genes, namely il1b, il12a, cxl34a.4, saa, irg1l, mmp9 and cebpb, were significantly upregulated by infection in the common 151 signature set." (PMID 35933481, 2022). "There was a significant increase in the levels of Il-1β mRNA detected at 6 h post infection in the hippocampi of rats with a UTI (1.97 ± 0.28, p = 0.025, unpaired Student’s t-test) as compared to mRNA levels in the hippocampi of sham rats (1.02 ± 0.12)." (PMID 35741412, 2022).
infection (continued). "Pro-inflammatory cytokines such as IL-1β mediate powerful inflammatory responses in fish after infection." (PMID 36452300, 2022). "In vivo study showed that infection with Burkholderiaceae resulted in the release of IL-1β and IL-18, the expression of inflammasome components and the death of lung epithelial cells." (PMID 35401192, 2022). "S. aureus USA300 infection caused overexpression of IL‐6, TNF‐α, and IL‐1β in serum, resulted in microglial over‐activation and excessive release of proinflammatory cytokines in the mPFC." (PMID 35977050, 2022). "The infection with West Nile virus (WNV) leads to increased production of IL-1β which is required for the migration of Langerhans cells to lymph nodes." (PMID 34201847, 2021). "It has been proven that the infection of macrophages with different bacteria strains e.g. Mycobacterium tuberculosis and Pseudomonas aeruginosa induces IL-1β secretion via the activation of an inflammasome." (PMID 34819075, 2021). "The MTB infection of primary human macrophages is shown to induce type I IFN signaling and limit the expression of IL-1β, which imparts immunity against the infection." (PMID 35198572, 2021). "Upon infection with Mtb, wild-type cells secreted large amounts of IL-1β in a dose-dependent manner." (PMID 34718331, 2021). "Recently, palmitoleate was also shown to inhibit TNFα, IL-1β and IL-6 proinflammatory cytokine responses in candida-infection stimulation analysis." (PMID 33886600, 2021). "Though IL-1β and IL-6 are less abundant in the S. aureus-infected airway, they still play important roles in infection outcomes." (PMID 34899759, 2021). "Twelve hours after infection, the levels of circulating inflammatory cytokines (IL-1β, IL-6, IL-18, and TNF-α) were still hardly detectable in most of the animals." (PMID 34236052, 2021). "Targeting NLRP3 to supress IL-1β production means IL-1β can still be produced by other pathways if the body encounters an acute infection." (PMID 34439904, 2021). "Further, within 3 days post infection reduced production of IL1β, CXCL2, and IL-6 and reduced neutrophil accumulation were observed although the burden of C. difficile had not changed." (PMID 34992590, 2021). "At 3 weeks after infection, the levels of IL-1β in BALF and IL-18 in serum from Aim2-/- mice are lower than that from WT mice." (PMID 33503864, 2021). "The NLRP3 inflammasome drives inflammation in response to tissue damage and infection by promoting the processing and release of IL‐1β." (PMID 33145969, 2021). "At the same time, IL-1β secretion stimulated by SFTSV infection or LPS/Nigericin was all repressed by inhibitor VX-765 on 48 h after infection." (PMID 33708197, 2021). "The results showed that the mRNA levels of TNF-α and IL-1β reached the peak at 24 h after infection with mutants of RmlA; also, the survival of the mutants in macrophage was sharply decreased compared with that of the WT." (PMID 33868202, 2021). "Local induction of cytokines including IL-1β and IL- 6 post infection of the mouse mammary gland with S. aureus was reported by Breyne and co-workers." (PMID 34827779, 2021). "The results demonstrated that NLRP3 assembly plays a crucial role in SFTSV infection induced IL-1β secretion." (PMID 33708197, 2021). "The observed infection augmented the cytokine level and also the viral load, as well as IL-1β and IL-6 in supernatant liquids and also in viral RNA within cells." (PMID 33937285, 2021). "Heterologous expression of MAG1 in BMDM inhibited IL-1β release compared to infection in normal BMDM." (PMID 34006649, 2021). "We also found that renal fibroblasts, but not renal epithelial cells, induced a significantly increased gene expression of pro-IL-1β (120-fold) after 4 h of CFT073 infection at MOI 1 compared to unstimulated cells." (PMID 34944029, 2021). "IL-1β and IL-36γ are both processed to their active forms by the protease SpeB, secreted by Streptococcus pyogenes during infection." (PMID 35003136, 2021).